OCLN (occludin)
Diseases named in the same sentence as OCLN in open-access papers (continued):
Sharing a sentence is not in itself a finding about the gene and the disease.
endometrial cancer (6 papers, 2013 to 2025). Primary or metastatic malignant neoplasm involving the endometrium (mucous membrane that lines the endometrial cavity). "Investigations into the role of TJ deregulation in endometrial cancer have primarily focused on the expression of CLDNs and OCLN." (PMID 36484008, 2022). "Further, we observed overexpression of an additional three genes in 8 of the 9 endometrial cancer cell lines: OCLN (occludin), F11R (JAM-A) and TJP3 (ZO-3)." (PMID 36484008, 2022). "Currently relevant information found occludin expression to be low in a variety of tumors, such as endometrial cancer tissue and in human prostate cancer tissue." (PMID 24245968, 2013). "In addition to the expected frequent overexpression of the much studied CLDN-3, CLDN-4 and OCLN genes, we also observed overexpression of an additional 21 TJ genes in at least one of the endometrial cancer cell lines." (PMID 36484008, 2022). "Specifically, we have confirmed the role of deregulated CLDN and OCLN genes (which encode integral membrane proteins) and provided strong additional evidence for deregulated F11R (JAM-A) and TJP3 (ZO-3) in the development of endometrial cancer." (PMID 36484008, 2022). "Occludin expression decreased progressively in parallel with the increase in carcinoma grade, and the decreased occludin expression correlated with myometrial invasion and lymph node metastasis in endometrial carcinoma." (PMID 27398181, 2016). "Whereas, the vast majority of studies have shown overexpression of CLDNs 3 and -4, levels of OCLN and JAM-A TJ membrane proteins have been found to be decreased in endometrial cancer 15-16." (PMID 36484008, 2022).
infarction (6 papers, 2018 to 2025). A localised pathological necrosis of tissue resulting from obstruction of the blood supply usually by a thrombus, an embolus, or vascular torsion. "Therefore, we investigated the expression of occluding in the colon and found the loss of occludin attributed to elevated gut permeability and microbial translocation post-infarction." (PMID 29615110, 2018). "A number of studies noted increased gut and brain permeability post-infarction through increases in TLR4 expression or reduced expression of tight junction proteins (occludin and ZO-1)." (PMID 40485663, 2025). "The tight junction protein occludin expression was suppressed in the peri-infarction tissue after ischemia-reperfusion, whereas miR-29a-5p agomir treatment partly restored its expression, as shown by Western blot analysis." (PMID 40529227, 2025). "This may compensate for the decrease in occludin expression after infarction." (PMID 36806348, 2023). "Unexpectedly, these factors including age, atrial fibrillation, TOAST classification, uric acid, white blood cell count, neutrophil percentage and serum levels of occludin, failed to predict HT after infarction." (PMID 41408503, 2025).
Insulin resistance (6 papers, 2020 to 2024). Increased resistance towards insulin, that is, diminished effectiveness of insulin in reducing blood glucose levels. "↓Hyperlipidemia, insulin resistance, glucose tolerance, endotoxemia-induced inflammation; ↑Intestinal barrier integrity; ↓ZO-1 and occludin protein levels." (PMID 37396125, 2023). "In contrast, ZO-1 and occludin were upregulated in the SAL intervention group and these responses may have partially contributed to the relatively lower insulin resistance observed in these rats." (PMID 32265702, 2020).
liver cirrhosis (6 papers, 2015 to 2025). "Compared to healthy individuals, the expression levels of Occludin and Claudin-1 in intestinal epithelial cells were reduced in patients with liver cirrhosis, negatively correlated with the Child-Pugh score." (PMID 39234554, 2024). "A novel study has shown that Escherichia coli (belonging to the family Enterobacteriaceae) isolated from patients with liver cirrhosis can damage the intestinal barrier by reducing the expression of Occludin and E-cadherin." (PMID 36159870, 2022). "Our animal experiment indicated that occludin and claudin-1 decreased during liver cirrhosis development, endotoxin in portal system was also found elevated due to the tight junction dysfunction in liver cirrhotic rats." (PMID 26152281, 2015). "Additionally, this two excellent case control studies indicated occludin, claudin-1 and claudin-2 as the significant altered tight junction proteins during the liver cirrhosis decompensating process." (PMID 26152281, 2015).
ovarian carcinoma (6 papers, 2013 to 2024). A malignant neoplasm originating from the surface ovarian epithelium. "Our results show that occludin expression in is low in comparison with its expression in ovarian serous adenomas, occludin expression is less in poorly differentiated ovarian carcinoma than in well-differentiated tumors." (PMID 24245968, 2013). "The correlation between the reduced expression of connexin 43, E-cadherin, occludin, and desmoglein in normal cells (the peritoneal mesothelium) and the increased invasiveness of cancer cells has been previously demonstrated in various ovarian cancer cell lines." (PMID 39595551, 2024). "Expression of claudin-6, occludin, and MMP2 was detected in samples of human ovarian cancer tissues by immunohistochemistry and correlated with the clinical properties of the tumors." (PMID 24245968, 2013). "Correlation between the expression of claudin-6, occludin and MMP-2 was evaluated in ovarian carcinoma specimens by McNemar test." (PMID 24245968, 2013). "Subsequently, the survival and immune infiltration analysis demonstrated that the upregulation of five candidate genes, ITGB2, VEGFA, CLDN4, OCLN, and SPP1, were correlated with an unfavorable clinical outcome and increased immune cell infiltration in ovarian cancer." (PMID 36980477, 2023). "Similarly, studies concerning the correlation of claudin-6, occludin and MMP-2 with ovarian cancer have rarely been reported." (PMID 24245968, 2013). "The expression of claudin-6 and occludin in ovarian cancer was not correlated with patient age, pathological grade, clinical stage, and metastasis (P > 0.05)." (PMID 24245968, 2013). "In the present study we observed coexpression of E-cadherin and N-cadherin in the TGF-β treated ovarian cancer cells without changes of morphological feature, slight decrease of occludin, and reduced transepithelial resistance all indicating dysfunctional tight junctions." (PMID 25278811, 2014). "Although this result was not statistically significant, it suggests that occludin expression in ovarian cancer may play a role in the occurrence and development of ovarian tumors." (PMID 24245968, 2013). "Our correlation studies showed that expression of the TJ proteins claudin-6, occludin and MMP-2 were not correlated in ovarian cancer." (PMID 24245968, 2013). "There were no apparent correlations between expression of claudin-6, occludin and MMP-2 in ovarian cancer tissue (P > 0.05)." (PMID 24245968, 2013).
acute pancreatitis (5 papers, 2019 to 2025). An acute inflammatory process that leads to necrosis of the pancreatic parenchyma. "Previous study in our laboratory showed that dietary supplementation of pectin could enhance intestinal barrier function, increase the expression of Claudin-4 and Muc-2 in the cecum of piglets, and abolish the abnormal expression of ZO-1 and Occludin caused in the acute pancreatitis model." (PMID 36569061, 2022). "In acute pancreatitis rat model, miR-122 can regulate the expression of Occludin to destroy intestinal barrier function and promote the development of acute pancreatitis." (PMID 40338929, 2025). "While, rats in the severe acute pancreatitis + butyrate group showed mitigated histologic lesions (P < .05) and increased expressions of occludin and ZO-1." (PMID 35943149, 2022). "Compared to rats in the control, rats in the severe acute pancreatitis group showed significantly higher pathohistological scores (P < .001) in the intestine, as well as decreased expression of occludin and ZO-1." (PMID 35943149, 2022). "Similarly, reported that butyrate significantly increased the expression of Occludin, Claudin-1, and ZO-1 in a rat model of severe acute pancreatitis with intra-abdominal hypertension." (PMID 38731359, 2024).
atopic dermatitis (5 papers, 2021 to 2025). "At the mRNA level, calcitriol enhanced the expression of claudin-1, occludin, and tight junction protein 1 (Tjp1, gene encoding ZO-1) in NC/Nga mice with atopic dermatitis." (PMID 37298299, 2023). "Furthermore, alteration of occludin has been associated with psoriasis and atopic dermatitis, which suggests it plays an important role in skin barrier function." (PMID 33603823, 2021). "MiR-155-5p can indirectly reduce the expression of Cldn1 and occludin by binding to protein kinase inhibitor α, thereby increasing skin barrier permeability and contributing to the onset of atopic dermatitis." (PMID 40940777, 2025). "In patients with atopic dermatitis, it has been reported that the mRNA expression of filaggrin, loricrin, occludin, and claudin-1 was decreased, while the expression of involucrin and TJP1 was not affected compared with control subjects." (PMID 37298299, 2023). "Among these tight junction components, only the mRNA expression of occludin was decreased in NC/Nga mice with atopic dermatitis compared to normal mice." (PMID 37298299, 2023). "We observed a decreased expression of claudin-1, occludin, and ZO-1 in the epidermis of NC/Nga mice with atopic dermatitis compared with control mice." (PMID 37298299, 2023). "Immunohistochemical analysis showed that filaggrin, involucrin, loricrin, claudin-1, occludin, and ZO-1 were decreased in NC/Nga mice with atopic dermatitis, which is consistent with previous reports." (PMID 37298299, 2023). "Comparable to atopic dermatitis skin, claudin-1 was redistributed upon cytokine treatment and occludin and ZO-1 patterns were also changed." (PMID 37289055, 2023). "The decreased expression of tight junction proteins such as occludin and ZO-1 has been reported in NC/Nga mice with atopic dermatitis." (PMID 37298299, 2023). "Studies have reported that quercetin pretreatment could upregulate the mRNA expression of Occludin and E-cadherin to promote wound healing in atopic dermatitis (AD)-induced cells." (PMID 38927100, 2024). "At the mRNA level, involucrin and occludin were downregulated, while the expression of filaggrin, loricrin, claudin-1, and Tjp1 was not changed in NC/Nga mice with atopic dermatitis." (PMID 37298299, 2023).
bladder cancer (5 papers, 2022 to 2025). "Occludin was further reported to promote angiogenesis experimentally in vivo in bladder cancer." (PMID 38141113, 2024). "siRNA mediated knockdown of DAB2 expression in UM-UC-3 bladder cancer cells was associated with reduced tumour formation in vivo and subsequent enhanced expression of EMT marker KRT14 and reduced expression of the mesenchymal to epithelial transition (MET) marker occludin (OCLN)." (PMID 36614139, 2022).
cerebral malaria (5 papers, 2009 to 2024). A sequestration of Plasmodium falciparum in the brain, which can cause coma and/or seizures. "This key step in cerebral malaria occurs via alterations in the expression levels of tight junction proteins, such as occludin (OCLN) and ZO-1 (also known as TJP1)." (PMID 35815443, 2022). "In the setting of infection such as cerebral malaria, ZO-1, occludin, and vinculin are downregulated." (PMID 30259344, 2018). "Destruction of EC-junction proteins--ZO-1, occludin and vinculin--in cerebral malaria has been reported." (PMID 24884882, 2014). "Those cultured with samples from severe malaria had no change in mRNA levels, and HUVECs cultured with P. falciparum from patients with cerebral malaria had decreased mRNA levels of occludin, vinculin, and ZO-1." (PMID 19680452, 2009). "When co-cultured with Pf-iRBC, we show evidence of key features involved in the pathogenesis of human cerebral malaria, including a decrease in TEER, increase in paracellular sodium fluorescein permeability, and disruption of ZO-1, occludin, and claudin-5 localization after 6 h of co-culture." (PMID 38693577, 2024).
Cirrhosis (5 papers, 2019 to 2024). A chronic disorder of the liver in which liver tissue becomes scarred and is partially replaced by regenerative nodules and fibrotic tissue resulting in loss of liver function. "We have previously reported that the expression of claudin 1 and occludin is decreased in the intestinal epithelial cells of cirrhotic patients, especially in decompensated cirrhosis, indicating gut barrier impairment." (PMID 35308545, 2022). "Intestinal zonula occludens-1, occludin, and alpha-5-defensin expression in the ileum correlated with SHP and decreased in patients with decompensated cirrhosis as compared to controls." (PMID 38332428, 2024). "In bile duct ligation (BDL), a model of cholestasis and cirrhosis, barrier integrity is restored in ileum of rats by treatment with OCA via increased expression of TJPs claudin-1 and occludin." (PMID 34831429, 2021). "In another cirrhosis model, OCA leads to an increase in expression of ZO-1 and occludin." (PMID 34831429, 2021).
food allergy (5 papers, 2016 to 2024). Gastrointestinal disturbances, skin eruptions, or shock due to allergic reactions to allergens in food. "For example, trachelogenin from Trachelospermi caulis extract has been reported to attenuate the symptoms of OVA-induced food allergy by enhancing the expression of occludin." (PMID 29143798, 2017). "We therefore investigated whether baicalein could regulate intestinal barrier function in our mouse model of food allergy by examining the TJ proteins claudin-1, occludin, ZO-1, and JAM-1 in the intestinal epithelium." (PMID 27561877, 2016). "Food allergy reduced the expression of ZO-1 and Claudin-1 in intestinal epithelial cells, but did not affect Occludin expression." (PMID 34684316, 2021).
HIV-1 infection (5 papers, 2014 to 2023). The type species of lentivirus and the etiologic agent of acquired immunodeficiency syndrome (AIDS). "BBB damage during HIV-1 infection has been associated with modified expression of tight junction (TJ) proteins, including occludin." (PMID 37840143, 2023). "In addition, this data raises the prospect that patients with inflammatory diseases with lower occludin expression may be more susceptible to HIV-1 infection." (PMID 37840143, 2023). "At present, two complementary molecular pathways of occludin regulating HIV-1 infection have been identified in human brain pericytes." (PMID 37840143, 2023). "Recent evidence indicates a bidirectional connection between HIV-1 infection and changes in occludin protein expression levels, pointing to occludin as a critical regulator in HIV-1 infection." (PMID 37840143, 2023). "Recently, occludin has attracted importance due to its newly discovered metabolic functions and its role in controlling HIV-1 infection." (PMID 37840143, 2023). "The current work further contributes to our knowledge on occludin being a novel regulator of host defense against HIV-1 infection in the neurovascular unit." (PMID 37209263, 2023). "In contrast, occludin overexpression in HIV-infected human brain pericytes decreased the rate of HIV-1 infection as measured by p24 levels by approximately 50%." (PMID 37840143, 2023). "Studies suggest that occludin expression levels and the rate of HIV-1 infection share a reverse, bidirectional relationship; however, the mechanisms of this relationship are unclear." (PMID 37840143, 2023). "Recently, occludin has attained additional importance, not only for its role in maintaining the integrity of TJs, but also for its influence on cellular metabolism and regulation of HIV-1 infection." (PMID 37840143, 2023). "We propose that occludin may serve as a potential therapeutic target to control HIV-1 infection and to improve the lives of people living with HIV-1." (PMID 37840143, 2023). "In this review, we describe the pathways involved in the regulation of HIV-1 infection by occludin." (PMID 37840143, 2023). "One of the newly identified functions of occludin is its involvement in regulating HIV-1 infection." (PMID 37840143, 2023). "We propose that a better understanding of the occludin-HIV-1 infections may identify occludin as a possible target to control HIV-1 infection and improve the life of people living with HIV-1." (PMID 37840143, 2023). "Interestingly, HIV-1 infection of pericytes can be regulated by occludin and a number of occludin regulated host genes." (PMID 34915908, 2021). "However, the mechanisms involved in the regulatory interaction between occludin and HIV-1 infection remain largely unknown." (PMID 37840143, 2023). "Unfortunately, no preclinical study has focused on occludin as a possible target in HIV-1 infection." (PMID 37840143, 2023). "The present review describes the cross-talks between phosphorylation of occludin and regulation of HIV-1 infection; however, it is not fully understood whether these are unrelated or causative associations." (PMID 37840143, 2023).
hyperuricemia (5 papers, 2021 to 2024). An abnormally high level of uric acid. "In addition, hyperuricemia model mice caused by abnormal purine metabolism can also cause intestinal epithelial damage and reduce the expression of ZO-1 and occludin." (PMID 38026929, 2023). "A similar study noted that L. paracasei MJM60396 decreased purine absorption and lowered the UA concentration in serum, inhibited expression of XOD, restored the intestinal barrier, and upregulated the levels of Zo-1 and Occludin in hyperuricemia mice." (PMID 38674582, 2024). "According to our results, supplementation of MJM60396 significantly increased the expression of intestinal ZO-1 and occludin, whose expression was reduced in the hyperuricemia group." (PMID 35630296, 2022). "The expression of occludin in the hyperuricemia group significantly decreased compared with the control group (Control vs. Hyperuricemia, p = 0.0232)." (PMID 35630296, 2022). "A recent study pointed out that intestinal barrier dysfunction was reflected by the downregulation of the expression of ZO-1, occludin and claudin-1, leading to hyperuricemia in mice." (PMID 35736894, 2022). "Inulin treatment prevented hyperuricemia-induced barrier damage via enhancing the expression levels of occludin and ZO-1 in the intestinal epithelium." (PMID 33104864, 2021). "Although the expression of occludin was not recovered in the allopurinol and MJM60662 groups, it was recovered in the MJM60396 groups compared with the hyperuricemia group (Hyperuricemia vs. MJM60396, p = 0.0154)." (PMID 35630296, 2022).
obstructive jaundice (5 papers, 2013 to 2024). A finding indicating increased bilirubin levels in the blood and urine, due to intrahepatic or extrahepatic obstruction of the biliary system. "Similarly, the occludin downregulation under OS post obstructive jaundice affects the brain capillaries by disrupting the BBB and it is also time dependent, directly associated with the increase of the superoxide radical level." (PMID 36434681, 2022).
osteoporosis (5 papers, 2021 to 2025). A condition of reduced bone mass, with decreased cortical thickness and a decrease in the number and size of the trabeculae of cancellous bone (but normal chemical composition), resulting in increased fracture incidence. "The expression of occludin, claudin, and ZO-1 was decreased in osteoporosis." (PMID 34721980, 2021). "Compared with the sham group, the expression of intestinal tight junction proteins ZO-1, claudin-1, and occludin was significantly reduced in the OVX group (p < 0.01), showing that the integrity of the gut barrier of osteoporosis mice induced by OVX was damaged." (PMID 38835486, 2024).